ACE (angiotensin I converting enzyme)
Diseases named in the same sentence as ACE in open-access papers (continued):
Sharing a sentence is not in itself a finding about the gene and the disease.
Hypertension (continued). "The IC50 value was 150 μg/mL, suggesting that T. algeriensis could be used as an ACE inhibitor to prevent and remedy hypertension." (PMID 37430944, 2022). "Therapy relies on the use of drugs that usually control hypertension and decrease blood pressure; being the most frequently used diuretics, β-blockers, calcium antagonists, angiotensin converting enzyme (ACE) inhibitors, and angiotensin II receptor blockers (ARBs)." (PMID 34207498, 2021). "Seventy-six percent of patients had at least one pre-existing comorbidity; the most frequent ones were arterial hypertension, cardiovascular disease and diabetes mellitus; 499 (30.6%) patients were on chronic therapy with angiotensin-converting enzyme (ACE) and/or angiotensin-II inhibitors." (PMID 35104305, 2021). "One of the key enzymes involved in hypertension is angiotensin-converting enzyme (ACE)." (PMID 33924574, 2021). "Hence, angiotensin II receptor blockers and ACE-inhibitors are pivotal in the treatment of hypertension and cardiovascular disorders." (PMID 34440064, 2021). "At the same time, she was started on ACE inhibitors for systemic hypertension." (PMID 34350147, 2021). "In hypertension, inhibition of ACE and/or elevation of ACE2 activities reduce BP." (PMID 33809620, 2021). "ACE inhibitors, which are widely used in cardiovascular therapy, such as for hypertension and congestive heart failure, may have a potential role in restoring the role of EPCs in repair, healing, and neovascularization." (PMID 34707860, 2021). "Angiotensin II receptor blockers (type 1 diabetes: W1, 18.0%; W7, 30.6%; type 2 diabetes: W1, 24.2%; W7, 43.6%) were increasingly used over ACE inhibitors after W1 (type 1 diabetes: W1, 65.0%; W7, 55.9%; type 2 diabetes: W1, 55.7%, W7, 41.1%) among patients diagnosed with hypertension." (PMID 33594476, 2021). "The potential mechanism in the management of hypertension through the inhibition of ACE involves the control of the production of nitric oxide (NO) by the regulatory mechanism of the renin-angiotensin-aldosterone system (RAAS) with ACE inhibition as a fundamental regulator of blood pressure." (PMID 35011441, 2021). "Therefore, the inhibition of ACE activity is a useful treatment for controlling hypertension and thus maintaining blood pressure within a normal range." (PMID 34940650, 2021). "Interestingly, hypertension is among the most common comorbidities in hospitalized COVID-19 patients, and is often treated with angiotensin II receptor blockers or angiotensin-converting enzyme (ACE) inhibitors." (PMID 33692695, 2021). "We also observed the antiplatelet therapeutic clopidogrel, the anti-hypertension medications losartan, irbesartan and valsartan, an ACE inhibitor medication enalapril, blood lipid lowering atorvastatin, sulfonylurea-class glipizide and gliclazide among the DM patients, but mostly in DKD patients." (PMID 33918080, 2021). "Therefore, compounds, including food ingredients, are being sought to inhibit ACE activity and support the pharmacotherapy of hypertension." (PMID 34959917, 2021). "Vasoconstriction occurs in the increasing state of ACE/Ang II and it might be possible that ACE/Ang II-induced hypertension may provoke hypertension-end organ damage by suppressing endothelial nitric oxide synthase activity." (PMID 33442728, 2021). "Controlling hypertension with ACE inhibitors and ARBs, results in an up regulation of ACE2." (PMID 33451360, 2021). "Concordantly to the most prevalent chronic condition hypertension and in consistence with the respective recommended first-line treatment the most frequently prescribed drug classes were ARBs/ACE-inhibitors (83%) with ARBs being slightly more frequently used than ACE-inhibitors." (PMID 33743582, 2021). "ACE is blocked by inhibitors used in hypertension treatment." (PMID 33925881, 2021). "Prior to her arrival to the ED, she was restarted on ACE inhibitors to manage her hypertension." (PMID 34436994, 2021).
Hypertension (continued). "Mechanistically, the risk factor hypertension for a severe COVID-19 course, could be linked to the use of angiotensin-converting enzyme (ACE) inhibitors and angiotensin receptor blockers (ARBs) to treat patients with hypertension." (PMID 34223911, 2021). "Therefore, ACE-inhibitory peptides have been considered as potent alternatives to synthetic ACE inhibitors in the treatment of hypertension." (PMID 34940650, 2021). "In case of hypertension, combined use of amlodipine and an ACE inhibitor is beneficial." (PMID 34351937, 2021). "Briefly, ACE can convert angiotensin I (Ang I) into angiotensin II (Ang II) and increase blood pressure by vasoconstriction, which is considered a useful therapeutic target for the treatment of hypertension." (PMID 33920763, 2021). "Thus, the food-derived ACE inhibitors have become popular in hypertension management, making ACE an attractive target for drug discovery." (PMID 33807119, 2021). "Evidence shows that hypertension and diabetic patients, who therapeutically receive ACE inhibitors (ACEIs) and AT1R blockers (ARBs), have elevated ACE2 levels and could be at high-risk for COVID-19 infection." (PMID 33953641, 2021). "While ACEI and ARB exert their anti-hypertension effects through specific targets (ACE and AT1R), ACEI and ARB may have different effects on ACE2 and its interaction with the SARS-CoV-2 virus." (PMID 33735262, 2021). "Patients with hypertension are often treated with ACE-inhibitors and AT1R-blockers." (PMID 34086837, 2021). "ACE inhibitors are, thus, a class of drugs frequently used in the treatment of hypertension." (PMID 33807119, 2021). "ACE inhibitors appear to be ubiquitous and effective at lowering diet-induced hypertension." (PMID 33572056, 2021). "Moreover, DK reportedly improves BP control in hypertensive in vivo models via the ACE inhibitory activity for managing hypertension." (PMID 33921856, 2021). "Inhibition of ACE activity may help in blood pressure modulation, which is one of the ways to manage hypertension." (PMID 34069802, 2021). "ACE converts AngI into AngII via removing His-Leu from C-terminal, and inhibition of ACE is one of the strategies for preventingcardiovascular disease, especially for hypertension." (PMID 34567165, 2021). "Moreover, SARS-CoV-2 causes ACE/ACE2 balance disruption and RAAS activation, which leads ultimately to COVID-19 progression, especially in the patient with comorbidities, such as hypertension, diabetes mellitus, and cardiovascular disease." (PMID 34285711, 2021). "Synthetic inhibitors such as lisinopril, captopril and enalapril are used as drugs for the treatment of hypertension; and many ACE inhibitory natural products and peptides have also been reported in the literatures which come from various plants and animal sources." (PMID 34834066, 2021). "The risk factors due to cardiovascular disease might depend on the same mechanistic as the hypertension because of the use of ACE inhibitors and ARBs." (PMID 34223911, 2021). "Drugs that can upregulate the expression of ACE2, such as ARBs and ACE inhibitors, have been commonly used in patients with hypertension and other cardiovascular diseases to regulate blood pressure and reduce the mortality and morbidity events (Gulet al., 2021;Shibataet al., 2020;Yanget al., 2020)." (PMID 34912542, 2021). "Demographic data collected included age, gender, body mass index (BMI), comorbidities (hypertension, diabetes mellitus), and drug history—particularly angiotensin converting enzyme inhibitors (ACE inhibitors), angiotensin II receptor blockers and beta blockers." (PMID 33805325, 2021). "ACE, as a zinc-containing dipeptide carboxypeptidase, plays a vital role in the regulatory mechanism of blood pressure, including the renin angiotensin system and kallikrein kinin system, so that inhibiting ACE activity is considered as a key measure to treat hypertension." (PMID 33800877, 2021).
Hypertension (continued). "We previously showed that 2K1C hypertension increases the gastric retention of a liquid test meal in awake rats, prevented by treatment with aliskiren, captopril or losartan, blockers of renin, angiotensin-converting enzyme (ACE), and ATR1, respectively." (PMID 34777003, 2021). "Altogether, the lack of knowledge does not allow us to draw a causal conclusion on the risk factor associated with hypertension nor decide to stop the use of ACE inhibitors and ARBs." (PMID 34223911, 2021). "Therefore, prescription of ARBs for hypertension is more than 20-folds when compared to ACE inhibitors (24.5% vs. 1.5%) during monotherapy in Korea13." (PMID 33469103, 2021). "Since July 2020, infants with systemic hypertension and concern for LV diastolic dysfunction at our institution have received treatment with a long-acting ACE inhibitor, enalapril, according to a standardized protocol and strict serial Targeted Neonatal Echocardiography (TnECHO) monitoring." (PMID 34640535, 2021). "Furthermore, the ACE/AngII/AT1R axis is linked with cardiovascular disease, diabetes, and hypertension, which are all associated with higher mortality in COVID-19." (PMID 33824998, 2021). "Indeed, higher plasma levels of ACE have been reported when the D allele was present, accordingly, the ACE DD genotype has been established as an independent risk factor of CVD and hypertension." (PMID 33810312, 2021). "Therefore, effective therapeutic strategy targeting RAAS, such as ACEi and ARBs, through inhibition of ACE/AngII/AT1R axis is the commonest used drugs for hypertension." (PMID 33544293, 2021). "Therefore, the current study was designed to determine the possible association between ACE I/D polymorphism and T2DM and hypertension (HTN) in a population of Saudi Arabian participants." (PMID 33507688, 2021). "Numerous studies have suggested that aside from being a successful therapeutic approach for hypertension, angiotensin-I-converting enzyme (ACE) inhibitors (ACEI) (e.g., Captopril (Cap) and Ramipril) could also improve endothelial function." (PMID 34940654, 2021). "Interestingly, inhibition of the key enzyme in controlling hypertension, angiotensin-converting enzyme (ACE), in SO flesh was four times higher than in CO flesh, suggesting that strong inhibitors resided in SO flesh." (PMID 33924574, 2021). "Earlier researchers were concerned on whether patients with COVID-19 and hypertension who are taking an ACE inhibitor (ACEI) or angiotensin-receptor blocker (ARB) medication should seek another antihypertensive drug." (PMID 34016183, 2021). "Polymorphisms in the ACE gene, encoding one of the components of the renin–angiotensin–aldosterone system (RAAS), have been found to be associated with a variety of cardiovascular diseases, such as hypertension, myocardial infarction, and cardiomyopathy." (PMID 34750628, 2021). "Interestingly, the drug of choice in a diabetic patient with hypertension is ACE inhibitors to reduce diabetic nephropathy." (PMID 34198801, 2021). "Angiotensin-converting enzyme (ACE) inhibitors and/or in combination with calcium channel blockers (CCBs) are generally recommended as the first-line antihypertensive therapy for people with hypertension and kidney dysfunction." (PMID 33766008, 2021). "Currently, ACE inhibitors are considered to be the first-line treatment for hypertension." (PMID 34568409, 2021). "Angiotensin-Converting Enzyme (ACE) inhibitors are one of the treatments for hypertension." (PMID 33800149, 2021). "Thus, ACE inhibitors and ARBs are first-line medications for treating hypertension, chronic kidney disease, and heart failure." (PMID 34947975, 2021). "The prevalence of hypertension was higher in the asymptomatic groups than in the symptomatic groups, suggesting that antihypertension treatment, especially ACE inhibitors might be effective for COVID-19." (PMID 33869253, 2021). "ACE inhibition is regarded as important in regulating blood pressure and treating hypertension." (PMID 34564142, 2021).
Hypertension (continued). "These properties explain why ACE inhibitors are likely to have a positive effect on patients with hypertension, and may present further benefits in reducing CVDs." (PMID 34473745, 2021). "Notably, a previous study revealed that ECE regulates BP by inhibiting angiotensin-converting enzyme (ACE) in a rat model of hypertension." (PMID 33921856, 2021). "Similarly, fucoxanthin extracted from the species Sargassum wightii Greville showed antioxidant activity in vitro and inhibition of ACE, with potential application as a food ingredient to overcome hypertension." (PMID 34203174, 2021). "The contribution of chymase, one of the enzymes responsible for angiotensin II generation in non-ACE pathway, remains unclear in the development of hypertension." (PMID 34079459, 2021). "Due to substantial ACE-inhibitory activity, natural source, easy availability, and less side effects than a synthetic drug, the medicinal plants can be effectively used against hypertension after necessary in vivo study." (PMID 34834066, 2021). "ACE inhibitors had been initially reported as a medication to treat hypertension." (PMID 34947975, 2021). "ACE inhibitors, as Captopril, Enalapril, or Lisinopril, are usually used to treat hypertension." (PMID 33672674, 2021). "Enalapril is an ACE inhibitor which is commonly used as first line therapy for its afterload reduction effects in children or adolescents with heart failure, LV systolic dysfunction, or systemic hypertension." (PMID 34640535, 2021). "For example, most patients using ACE inhibitors for hypertension or other indications generally have more than one commitment medications, which could affect study results." (PMID 33976340, 2021). "In addition, no significant change in proCPU levels was observed in 12 patients with uncontrolled hypertension under an adequate dose of an ACE-inhibitor before and after the addition of an angiotensin-receptor blocker to their regimen." (PMID 33477318, 2021). "Therefore, angiotensin receptor blockers (ARBs) and angiotensin converting enzyme (ACE) inhibitors are commonly used in the treatment of arterial hypertension, heart failure or kidney disease." (PMID 34070168, 2021). "In addition, previous landmark clinical trials demonstrated the efficacy and safety of primarily once-daily dosing of ACE inhibitors to treat hypertension." (PMID 34567875, 2021). "As a result, inhibiting ACE is thought to be a useful strategy for treating hypertension." (PMID 34564142, 2021). "Commencing with diuretics in the 1950s, the available medications so far for the treatment of hypertension include calcium channel blockers (CCBs), angiotensin receptor blockers (ARBs), angiotensin-converting enzyme (ACE) blockers, and beta-adrenergic blocking agents (β-blockers)." (PMID 34198801, 2021). "The large proteins are usually unable to bind the active site of ACE, however, the smaller peptides generated by enzymatic hydrolysis could easily bind to the active site of ACE as inhibitor and thereby prevent high blood pressure." (PMID 35049866, 2021). "In contrast, high blood pressure is associated with both augmented lung ACE mRNA and ACE shedding from the cell surface, leading to increased serum ACE concentrations but not ACE cell surface lung protein abundance." (PMID 34751382, 2021). "Recent data of COVID-19 patients who received ACE inhibitors or AT1 antagonists as an accompanying therapy for their high blood pressure have been reported, with some studies demonstrating a positive effect on the survival rate of COVID-19 patients, and others exhibiting no benefit." (PMID 34440554, 2021). "Hence, ACE inhibitory peptides derived from natural sources are desired for the preventive therapy of high blood pressure." (PMID 33916201, 2021). "ACE inhibitors are widely used in patients with high blood pressure and chronic heart failure." (PMID 33670126, 2021).
Hypertension (continued). "Recent research has shown that inhibition of ACE with food derived peptides could be an effective way in the prevention/management of hypertension." (PMID 35049866, 2021). "Therefore, inhibition of ACE is an important molecular target in the prevention and management of hypertension." (PMID 34234885, 2021). "We aim to explore the potential influences of ACE inhibitors on a hospitalised patient population with hypertension and COVID-19 disease and determine whether continued usage may negatively impact patient outcomes." (PMID 32873147, 2020). "Furthermore, angiotensin-converting enzyme (ACE) inhibitors, which are commonly used for arterial hypertension, can also cause cough." (PMID 32819357, 2020). "Different classes of synthetic drugs are used to treat hypertension such as direct inhibitors of the renin-angiotensin system (ACE inhibitors, angiotensin receptor blockers), beta-adrenergic antagonists, diuretics, inhibitors of the calcium channel blockers and aldosterone receptors." (PMID 33171852, 2020). "ACE inhibitors are widely used as drugs for the treatment of hypertension." (PMID 32121598, 2020). "In addition to hypertension, the potentially beneficial or harmful effects of ACE inhibitors and ARBs used as an antihypertensive at the onset and the severity of SARS-CoV-2 infection have been discussed." (PMID 32599972, 2020). "Although ACE inhibitors are preferred for hypertension due to CKD, crisis episodes may require IV nicardipine therapy for rapid BP control since it has been used safely in children." (PMID 33194923, 2020). "Among various types of bioactive peptides, ACE-inhibitory peptides from food sources have been most extensively studied for their potential use as natural alternatives to drugs for reducing blood pressure through binding and inhibiting ACE, and thus preventing and managing hypertension." (PMID 32013233, 2020). "In hypertension ACE inhibitors are serving to restore the balance of ACE2 to ANG II formation." (PMID 32685191, 2020). "The ACE inhibitory effect and hypouricemic potential displayed by the triterpene are not only crucial in renal protection, but in other related complications such as cardiovascular disease, hypertension and gout arthritis as well." (PMID 32887389, 2020). "Due to these biological actions, it is well known that ACE inhibition could lead to major clinical benefits in patients with hypertension, heart failures, myocardial infarction, and other related diseases." (PMID 31940798, 2020). "In this brief correspondence piece, the authors postulate that patients with hypertension and diabetes treated with angiotensin-converting enzyme (ACE) inhibitors or angiotensin II type-I receptor blockers (ARBs) are at increased risk of developing severe and fatal COVID-19." (PMID 32586327, 2020). "They had a higher prevalence of dyslipidemia, hypertension and MI, which could probably explain the higher prescription of cardioprotective medications such as aspirin, statins and ACE-inhibitors/ARBs." (PMID 32103115, 2020). "Both hypertension and diabetes are often treated with ACE inhibitors and it has been suggested that altered ACE2 levels resulting from treatment may a contributor to disease severity in Covid-19." (PMID 33133024, 2020). "Angiotensin-converting enzyme/angiotensin receptor blocker (ACE/ARB) can be useful in patients with concomitant hypertension but its afterload reducing properties may be a particular concern in those with a significant LVOT gradient." (PMID 33500852, 2020). "As patients with hypertension or diabetes were commonly treated with ACE inhibitors and angiotensin II type-I receptor blockers, an upregulation in the expression of ACE2 was mentioned in previous studies, which perhaps led to the heart being more vulnerable to SARS-CoV-2 infection." (PMID 33226958, 2020). "Most of the medicinal plants used to treat hypertension possess ACE inhibitor activity." (PMID 32366012, 2020).